CDO1 (cysteine dioxygenase type 1)
Description:
Rate-limiting enzyme of the cysteine catabolic process to taurine, which catalyzes the oxidation of cysteine to cysteine sulfinic acid with addition of molecular dioxygen.
Synonyms: CDO-I
Tractability: Small molecule: a structure with a bound ligand is known. PROTAC: ubiquitination databases record sites on it.
Gene: Protein-coding gene on chromosome 5 (115,804,733 to 115,816,660, reverse strand). Ensembl gene ENSG00000129596.
Subcellular location (Human Protein Atlas): Nucleoplasm; Cytosol
Pathways (Reactome):
Metabolism: Degradation of cysteine and homocysteine
Gene Ontology:
Molecular function: cysteine dioxygenase activity; ferrous iron binding; zinc ion binding; nickel cation binding; iron ion binding; oxidoreductase activity, acting on single donors with incorporation of molecular oxygen, incorporation of two atoms of oxygen
Biological process: L-cysteine catabolic process; taurine biosynthetic process; lactation; response to amino acid; response to azide; response to cAMP; response to ethanol; response to glucagon; response to glucocorticoid; sulfur compound metabolic process
Cellular component: cytosol
Genetic constraint (gnomAD): Loss-of-function variants: 10 observed, 14.98 expected, observed/expected ratio (o/e) 0.67, 90% interval 0.41 to 1.13. The upper end of that interval is the gene's LOEUF score, 1.13, which puts it in group 4 of 6, group 1 being the genes least tolerant of losing a copy. Missense variants: 178 observed, 186.4 expected, observed/expected ratio (o/e) 0.95, 90% interval 0.84 to 1.08. Synonymous variants: 63 observed, 68.55 expected, observed/expected ratio (o/e) 0.92, 90% interval 0.75 to 1.13.
Homologues: Orthologues: chimpanzee CDO1 (100% identical), macaque CDO1 (99% identical), pig CDO1 (95% identical), dog CDO1 (94% identical), guinea pig CDO1 (94% identical), mouse Cdo1 (92% identical), rabbit CDO1 (92% identical), rat Cdo1 (92% identical), tropical clawed frog cdo1 (79% identical), zebrafish cdo1 (74% identical), Drosophila melanogaster CG5493 (52% identical), Caenorhabditis elegans cdo-1 (46% identical).
Diseases named in the same sentence as CDO1 in open-access papers:
CDO1 is named in the same sentence as 79 diseases in open-access papers, as found by Europe PMC text mining. Sharing a sentence is not in itself a finding about the gene and the disease. The quoted sentences say what the papers report.
lung carcinoma (23 papers, 2012 to 2026). "In this current study, we found that HOXA7 DNA methylation was correlated with higher NDI, and methylation of HOXA7, SOX17, ZFP42, HOXA9, CDO1 and TAC1was associated with advanced stage disease in lung cancer." (PMID 39107707, 2024). "Among the top 15 FC-specific hypermethylated genes, the methylation of ZSCAN31, KCNA3 and CDO1 were reported to be associated with lung cancer development." (PMID 35313869, 2022). "Studies reporting CDO1 promoter methylation in liquid biopsies (blood, urine, or sputum) for lung cancer detection with histological confirmation were included." (PMID 41602411, 2026). "Compared with the GGNs-original lung cancer, patients with mass original showed higher positive rates in CDO1 (P = 0.006) and RASSF1A methylation (P = 0.08), respectively." (PMID 38315228, 2024). "Collectively, this study reveals that the methylation of 7 genes (TAC1, CDO1, HOXA9, ZFP42, SOX17, RASSF1A and SHOX2) has a big significance in the diagnosis of lung cancer and achieved a diagnostic model with high sensitivity and specificity." (PMID 38315228, 2024). "This was corroborated by the identification of methylation-regulated genes (PCDH10, TBX2, and CDO1) recently described as biomarkers in localized lung cancers and premalignant lesions." (PMID 36461127, 2022). "For lung cancer risk prediction, univariate logistic regression analysis revealed that methylation levels of SOX17, HOXA9, CDO1, and TAC1 were significantly related to lung cancer risk." (PMID 36153611, 2022). "Twelve of 20 genes (60%) in the list were methylation driver genes described previously in lung cancer, such as CDO1, SLIT2, SOX17 and TCF21." (PMID 33859751, 2021). "In lung cancer, researchers also found a similar pattern that the promoter of CDO1 in tumor tissues is hypermethylated." (PMID 34246261, 2021). "Promoter methylation of eight lung cancer-specific genes (CDO1, TAC1, SOX17, HOXA7, HOXA9, GATA4, GATA5, and PAX5) was detected using nanoparticle-based DNA extraction (MOB) followed by qMSP." (PMID 32138766, 2020). "As elevated odds ratios ranged from 2.81 to 7.19, logistic regressions analyses also indicated that the methylation of CDO1, TAC1, SOX17, and HOXA7 were closely related to increasing lung cancer risk." (PMID 32138766, 2020). "CDO1 affected the procession of prostate cancer, clear‐cell renal cell cancer, breast cancer, and lung cancer." (PMID 32170852, 2020). "Detecting the methylation level of CDO1 has a potentially huge advantage for the early diagnosis of lung cancer." (PMID 32317090, 2020). "Overall, these results demonstrate that NRF2 and other mechanisms of intracellular CYS accumulation promote CDO1 accumulation, which leads to a selective growth disadvantage in lung cancer cells." (PMID 31107239, 2019). "By contrast, lung cancer cell lines accumulated significant CYS due to epigenetic silencing of the CDO1 locus." (PMID 31107239, 2019). "We find that Cdo1 accumulates in tumors from our Keap1R554Q/R554Q mutant lung cancer GEMM, which is correlated with a block in lung tumor formation." (PMID 31107239, 2019). "In breast cancer, gallbladder cancer, renal clear-cell cancer, esophageal squamous cell carcinoma, and lung cancer, methylation abnormalities in CDO1 have been reported as a prognostic factor." (PMID 29746493, 2018). "Of 30 top ranked genes, FAM107A, MAMDC2, SOX17, TCF21, PTPRH, and CDO1 have been previously reported with aberrant DNA methylation in lung cancer." (PMID 27610367, 2016). "The human CDO1 gene is located on chromosome 5 q23.2 which is frequently deleted in advanced lung cancer." (PMID 23028699, 2012). "In lung cancer, all tumors (100%, 10 of 10) displayed down-regulation of CDO1 (upper), while the expression of CDO1 in liver was too high to compare between normal and tumor tissues (not determined, n/d)." (PMID 23028699, 2012). "Interestingly, PCDH10, TBX2, and CDO1 were described as potential biomarkers for early-stage lung cancers." (PMID 36461127, 2022).
lung carcinoma (continued). "Methylation of CDO1 has been identified as a specific marker for lung cancer diagnosis." (PMID 35313869, 2022). "CDO1 is a metabolic liability for NSCLC, and the functional identification of cancer-specific methylation of CDO1 could be applied for the diagnosis of lung cancer." (PMID 33511215, 2021). "Therefore, this study aims to discuss the value of CDO1 methylation in the early diagnosis of lung cancer." (PMID 32317090, 2020). "Aiming at practical applications in which CDO1 methylation may serve as a biomarker, research on lung cancer, gastric cancer, colon cancer, HBV-related HCC, and cholangiocarcinoma has been conducted." (PMID 29746493, 2018). "Methylation of the CDO1 promoter region has been found in esophageal cancer, gastric cancer, colorectal cancer, cholangiocarcinoma, lung cancer, breast cancer, bladder cancer, prostate cancer, endometrial cancer, and hepatitis B virus-related hepatocellular carcinoma (HBV-related HCC)." (PMID 29746493, 2018). "They observed re-expression of the CDO1 after 5-Aza-dC treatment in lung cancer cell lines." (PMID 23028699, 2012). "To this end, we compared the DNA methylation status of 7 genes including TAC1, CDO1, HOXA9, ZFP42, SOX17, RASSF1A and SHOX2 in lung cancer cases with different stages." (PMID 38315228, 2024). "The results showed that the methylation rate of CDO1 and SHOX2 showed significantly different between the I-IV stages of lung cancer." (PMID 38315228, 2024). "In this study, we explored the significance of the DNA methylation of 7 genes including TAC1, CDO1, HOXA9, ZFP42, SOX17, RASSF1A and SHOX2 in the blood cfDNA samples in distinguishing lung cancer from benign nodules and healthy individuals." (PMID 38315228, 2024). "Then, we explored the diagnosis value of the DNA methylation status of 7 genes including TAC1, CDO1, HOXA9, ZFP42, SOX17, RASSF1A and SHOX2 in lung cancer." (PMID 38315228, 2024). "Here, we explored the significance of the DNA methylation of 7 genes including TAC1, CDO1, HOXA9, ZFP42, SOX17, RASSF1A and SHOX2 in the blood cfDNA samples in distinguishing lung cancer from benign nodules and healthy individuals." (PMID 38315228, 2024). "Here, we compared the DNA methylation status of 7 genes including TAC1, CDO1, HOXA9, ZFP42, SOX17, RASSF1A and SHOX2 in lung cancer cases with I–IV stages." (PMID 38315228, 2024). "Of note, promoter 5-mC levels of CDO1 and HOXA9 were previously utilized for plasma-based disease assessment in both early and advanced lung cancers." (PMID 36461127, 2022). "As the hypermethylated markers, CDO1 and PTGER4 were detected using plasma and sputum samples in early-stage lung cancers." (PMID 34620221, 2021). "In conclusion, despite these limitations, our meta-analysis advocates that methylated SOX17, CDO1, ZFP42, TAC1, FAM19A4, FHIT, MGMT, p16, and RASSF1A are useful biomarkers in the screening and auxiliary detection of lung cancer." (PMID 28644424, 2017). "While many biomarkers have been shown to be viable for gastric and urinary cancers such as bladder and CRC, one study also reported a successful DNA methylation analysis (1.7) of a panel (CDO1, TAC1, HOXA7, HOXA9, SOX17, and ZFP42 promoters) to diagnose lung cancer." (PMID 40141826, 2025). "Furthermore, the methylation positive rates of CDO1 and SHOX2 were different between I-IV stages of lung cancer." (PMID 38315228, 2024). "Moreover, we compared the DNA methylation status of 7 genes (TAC1, CDO1, HOXA9, ZFP42, SOX17, RASSF1A and SHOX2) in lung cancer cases from the mass and GGNs groups." (PMID 38315228, 2024). "Following a large literature review, we explored the performance of the DNA methylation of 7 genes including TAC1, CDO1, HOXA9, ZFP42, SOX17, RASSF1A and SHOX2 in the blood cfDNA samples in distinguishing lung cancer from benign nodules and healthy individuals." (PMID 38315228, 2024). "CDO1-LNC, a lncRNA annotated in the GENCODE (v28), was also detected in our lung cancer data." (PMID 33859751, 2021).
lung carcinoma (continued). "Therefore, we advocate that methylated SOX17, CDO1, ZFP42, TAC1, FAM19A4, FHIT, MGMT, p16, and RASSF1A are useful in the screening and auxiliary detection of lung cancer." (PMID 28644424, 2017). "The overall mean value of the CDO1 expression level in 10 patients without cancer was about 2.5 times higher (19.14±21.56) than that in 10 lung cancer patients (8.03±9.20) (lower)." (PMID 23028699, 2012). "This confirmed the utility of CDO1, TAC1, HOXA7, and SOX17, while newly tested genes were not as effective for lung cancer detection." (PMID 32138766, 2020). "Moreover, the methylation of other genes including E-cadherin, cysteine dioxygenase 1 (CDO-1), TERT and p16, which methylation are important for lung cancer development, were not significantly changed." (PMID 29467412, 2018).
gastric cancer (21 papers, 2012 to 2024). A primary or metastatic malignant neoplasm involving the stomach. "CDO1 promoter methylation was also associated with the risk of gastric cancer, breast cancer, hepatocellular carcinoma, and prostate cancer." (PMID 31956659, 2019). "It was considered that the CDO1 methylation together with its aberrant expression may be causatively involved in the distant metastasis, resulting in poor prognosis of gastric cancer." (PMID 30934021, 2019). "In RGC tumors, on the other hand, CDO1 hypermethylation is significantly associated with advanced disease stage, and E-cadherin hypermethylation was associated with advanced lymph node metastasis, which are consistent with previous studies of primary gastric cancer." (PMID 31069006, 2019). "Methylation of the Cdo1 promoter can be observed in various cancers, including colorectal cancer, breast cancer, and gastric cancer." (PMID 38672271, 2024). "Akin to CDO1, stearoyl-CoA desaturase 1 (SCD1), an enzyme associated with the endoplasmic reticulum that is significantly upregulated in gastric cancer tissues, is implicated in the conversion of saturated fatty acids to monounsaturated fatty acids." (PMID 38370477, 2024). "Studies of the effect of CDO1 methylation on the survival of cancer cells have shown that the suppression of CDO1 expression inhibits ferroptosis in gastric cancer cells." (PMID 38732110, 2024). "Suppression of CDO1 impedes Erastin-triggered ferroptosis in gastric cancer cells by augmenting intracellular levels of glutathione and the expression of GPX4, thereby abating the generation of reactive oxygen species and lipid peroxidation." (PMID 38370477, 2024). "For instance, Cdo1 plays a significant role in mediating Erastin-induced ferroptosis in gastric cancer cells." (PMID 38672271, 2024). "In gastric cancer, inhibiting CDO1 expression led to the restoration of glutathione levels, increased expression of GPX4, prevented ROS production, and reduced the production of malondialdehyde, which is a final product of lipid peroxidation." (PMID 37740473, 2023). "As the CpG islands methylator phenotype (CIMP) including MLH1 hypermethylation has been repeatedly proposed to be enriched in the specific patients, we finally compared MLH1 methylation and CDO1 methylation in gastric cancer." (PMID 34936649, 2021). "In gastric cancer, researchers found that CDO1 has significantly DNA hypermethylation than normal tissues." (PMID 34246261, 2021). "Combination of MLH1 and CDO1 methylation status has important prognostic information in gastric cancer, suggesting that prognosis is differentially affected by oncological function of the individual genes." (PMID 34936649, 2021). "We recently demonstrated that Cysteine dioxygenase type 1 (CDO1) hypermethylation was cancer-specific in primary gastric cancer and its hypermethylation was correlated with poor prognosis in the same patient cohort." (PMID 34936649, 2021). "In the current study, we clarified that CDO1 hypermethylation with MLH1 hypomethylation showed the worst prognosis in gastric cancer and vice versa." (PMID 34936649, 2021). "More interestingly, the higher the DNA methylation level of CDO1 in gastric cancer patients, the better the survival prognosis of patients receiving chemotherapy." (PMID 34246261, 2021). "We recently reported the usefulness of DNA diagnosis using the CDO1 gene methylation in DNA cytology test using the peritoneal lavage of gastric cancer." (PMID 30934021, 2019). "Gastric cancer patients were divided into two groups of H group (n = 47): high CDO1 TaqMeth V group (TaqMeth V ≥ 32.6) and L group (n = 91): low CDO1 TaqMeth V group (TaqMeth V <32.6)." (PMID 30934021, 2019). "In conclusion, CDO1 TaqMeth V was rigorously validated to be an important prognostic factor in primary gastric cancer." (PMID 30934021, 2019).
gastric cancer (continued). "Quantitative CDO1 methylation value (TaqMeth V) was initially calculated in 138 gastric cancer patients operated in 2005, and its clinical significance was elucidated." (PMID 30934021, 2019). "There have been reports of cancer-specific CDO1 methylation abnormalities in the gastrointestinal tract in esophageal cancer, stomach cancer and CRC." (PMID 30677088, 2019). "Promoter DNA of the CDO1 gene is frequently hypermethylated in human cancers including gastric cancer, which showed the highest AUC (0.95) to differentiate tumor tissues from the corresponding non-cancerous tissues." (PMID 30934021, 2019). "We rigorously assessed the clinical relevance of promoter DNA methylation of Cysteine dioxygenase type 1 (CDO1) gene, a cancer-specific aberration, in human gastric cancer." (PMID 30934021, 2019). "In the present study, CDO1 TaqMeth V was rigorously validated as prognostic factor of primary gastric cancer." (PMID 30934021, 2019). "The current study is the first report describing clinicopathological relevance of CDO1 gene promoter DNA methylation status in primary gastric cancer." (PMID 30934021, 2019). "In the case of patients with initial malignant disease, the initial non-cancerous gastric mucosa tissues that had surrounded the initial cancer are thought to harbor methylation events, especially for CDO1, that are risky for remnant gastric cancer." (PMID 31069006, 2019). "Promoter DNA hypermethylation of CDO1 gene was rigorously validated as an important prognostic biomarker in primary gastric cancer with specific stage." (PMID 30934021, 2019). "The CDO1 full length vector was transfected to all 6 gastric cancer cell lines and the expression was confirmed by RT-PCR and Western blotting." (PMID 30934021, 2019). "Similar CDO1 methylation traits were confirmed in various other cancers such as breast, esophageal, lung, bladder, and gastric cancer." (PMID 25469504, 2014). "Notably, cysteine dioxygenase 1 (CDO1) assumes a pivotal role in the mechanism of iron-dependent cell death provoked by Erastin in gastric cancer cells." (PMID 38370477, 2024). "Whereas cysteine dioxygenase 1 (CDO1) expression is lost due to its hypermethylated promoter across a range of cancer types including gastric cancer (GC), its functions and molecular underpinnings remain largely unknown." (PMID 36526626, 2022). "Additionally, one previous report validated that higher CDO1 gene methylation independently predicted worse prognosis in patients with gastric cancer." (PMID 36526626, 2022). "Q-MSP for CDO1 gene was initially performed in 138 primary gastric cancer." (PMID 30934021, 2019). "The recurrence pattern of pStage II/III gastric cancer patients with no adjuvant chemotherapy in the expanded set was then clarified to explain the cause of poor prognosis by CDO1 gene hypermethylation." (PMID 30934021, 2019). "In our current study, CDO1 gene promoter methylation definitely accumulates as disease progressed, and it was significantly associated with the initial recurrences at distant organs in pStage III gastric cancer." (PMID 30934021, 2019). "In the present study, CDO1 gene promoter DNA methylation was for the first time examined and clarified for detailed clinicopathological factors in primary gastric cancer, and proved great clinical value in gastric cancer clinics." (PMID 30934021, 2019). "A high frequency of CDO1 promoter methylation in colon cancer was then identified when compared with normal colon, and findings were extended to several other malignancies, including breast, esophagus, lung, bladder, and gastric cancer." (PMID 24351290, 2014). "Additionally, CDO1 shows promising diagnostic value in a few tumor types; for example, it could be an efficient strategy to determine minimal residual disease of the peritoneum in patients with gastric cancer (GC)." (PMID 36526626, 2022). "The suppression of CDO1 increased the expression of GSH and inhibited ferroptosis in gastric cancer." (PMID 34820377, 2021).